EIF4A3 (eukaryotic translation initiation factor 4A3)
Diseases named in the same sentence as EIF4A3 in open-access papers (continued):
Sharing a sentence is not in itself a finding about the gene and the disease.
atherosclerosis (1 paper, 2024). A disease characterized by the build-up of fatty material and calcium deposition in the arterial wall resulting in partial or complete occlusion of the arterial lumen. "A circRNA hsa_circ_0030042 inhibits abnormal autophagy in HUVECs and improves atherosclerosis in vivo by recruiting eukaryotic initiation factor 4A-III (eIF4A3)." (PMID 39199340, 2024).
Atrophy (1 paper, 2025). Any weakening or degeneration, especially through lack of use. "Our results reveal a significant correlation between EIF4A3 and muscle atrophy, suggesting that increased EIF4A3 levels play a role in the progression of muscle atrophy." (PMID 40641186, 2025).
colitis (1 paper, 2024). Inflammation of the colon. "CircHIPK2 mediated by FUS, interacts with EIF4A3 to promote the translation of TAZ, ultimately increasing the transcription of downstream target genes CCN1 and CCN2, to contribute to cell growth in intestinal epithelial of colitis and CRC." (PMID 38981023, 2024).
esophageal tumor (1 paper, 2024). "Importantly, upregulation of eIF4A3 and circ-231 in esophageal tumor tissues was observed, compared to adjacent normal tissues." (PMID 38577609, 2024). "Moreover, fluorescent co-localization analysis demonstrated that circ-231 was co-localized with eIF4A3 in cytoplasm in human esophageal tumor cells." (PMID 38577609, 2024).
gallbladder cancer (1 paper, 2021). "In conclusion, knockdown of circSMAD2 inhibits the tumorigenesis of gallbladder cancer through binding with eIF4A3." (PMID 34727877, 2021). "Knockdown of circSMAD2 inhibits the tumorigenesis of gallbladder cancer through binding with eIF4A3." (PMID 34727877, 2021).
influenza (1 paper, 2019). An acute viral infection of the respiratory tract, occurring in isolated cases, in epidemics, or in pandemics; it is caused by serologically different strains of viruses (influenzaviruses) designated A, B, and C, has a 3-day incubation period, and usually lasts for 3 to 10 days. "Hence, these eIF4A3 inhibitors have potential in the development of new anti-influenza drugs." (PMID 31379779, 2019).
medulloblastoma (1 paper, 2020). A malignant, invasive embryonal neoplasm arising from the cerebellum. "The roles of ACTL6A, EIF4A3, ENAH, and UMPS in medulloblastoma had not been reported." (PMID 33101383, 2020).
metastatic tumors (1 paper, 2021). "Furthermore, we examined the therapeutic effect of eIF4A3-IN-2 on BC-BM, which eIF4A3-IN-2 treatment was started when bioluminescence signal of bone-metastatic tumors reached 2 × 105 p/sec/cm2/sr." (PMID 34325714, 2021).
myotonic dystrophy (1 paper, 2017). An inherited progressive disorder affecting the muscles. "In many cases DUX4-induced cells with EIF4A3 aggregates appeared to have reduced nuclear staining beyond the aggregates suggesting that the majority of EIF4A3 was redistributed to the dsRNA foci, similar to the depletion of MBNL proteins by the mutant nuclear RNA in myotonic dystrophy." (PMID 28273136, 2017).
osteoporosis (1 paper, 2025). A condition of reduced bone mass, with decreased cortical thickness and a decrease in the number and size of the trabeculae of cancellous bone (but normal chemical composition), resulting in increased fracture incidence. "The EIF4A3 mRNA did not change in the alveolar bone of postmenopausal women with (P11–P20) or without osteoporosis (P1–P10) according to RT‐qPCR analysis." (PMID 40051055, 2025).
periodontitis (1 paper, 2025). An acute or chronic inflammatory process that affects the tissues that surround and support the teeth. "Via validated axes like hsa_circ_0084054/miR‐508‐3p/PTEN, our bioinformatic predictive model identified hsa_circ_0003563/EIF4A3/miR‐23‐5p and hsa_circ_0001161/miR‐665 as potential regulators of immune response and inflammation in periodontitis." (PMID 40590107, 2025).
polymyalgia rheumatica (1 paper, 2018). A syndrome characterized by pain, stiffness, and tenderness of the proximal muscle groups including the shoulder, pelvic girdle and the neck. "PPP1CB and EIF4A3 were shared by both jaw claudication and a background history of Polymyalgia Rheumatica (PMR)." (PMID 30037347, 2018).
renal cell carcinoma (1 paper, 2025). "This study reveals that circPVT1 promotes the renal cell carcinoma lung metastasis and tumor progression through encoding the cP104aa peptide and directly binds with EIF4A3, which jointly regulates the target gene c‐MYC." (PMID 40966379, 2025).
sarcoma (1 paper, 2025). A usually aggressive malignant neoplasm of the soft tissue or bone. "Lacking an internal ribosome entry site (IRES) for translation capability, its biogenesis is facilitated by the RNA-binding proteins FUS (fused in sarcoma) and eIF4A3 (eukaryotic translation initiation factor 4A3), with upstream regulation by cAMP-response element-binding protein (CREB)." (PMID 40662732, 2025).
Sepsis (1 paper, 2025). Sepsis is defined as life-threatening organ dysfunction caused by a dysregulated host response to infection. "Mechanistically, RNA pull-down and RNA RIP assays demonstrated that hsa_circ_0074158 directly binds to the RNA-binding protein (RBP) EIF4A3, which decreases the stability of CTNNA1 (mRNA) and the production of α-catenin, subsequently impairing endothelial barrier function in sepsis." (PMID 41058681, 2025).
thyroid carcinoma (1 paper, 2023). "In contrast, EIF4A3 expression was lower in kidney chromophobe, kidney renal clear cell carcinoma, and thyroid carcinoma compared to the normal tissues." (PMID 37180585, 2023).
tumor (76 papers, 2011 to 2026). "Multiple regression models for tumor eIF4a3 levels confirmed the positive association between eIF4a3 and SELENOF." (PMID 41563517, 2026). "Multivariate ordinal logistic regression models revealed that higher eIF4a3 levels are associated with higher tumor stage (OR = 1.64, 99% CI = 1.10–2.46, p-value = 0.002)." (PMID 41563517, 2026). "eIF4A3 is up-regulated in several type of cancers and associated with tumor progression and oncogenesis." (PMID 38577609, 2024). "Further studies are necessary to elucidate the underlying molecular mechanisms of EIF4A3 in tumor progression and immunity." (PMID 37777564, 2023). "Our analysis revealed a significant correlation between EIF4A3 expression levels and immune scores in 23 out of 44 cancer types, indicating that EIF4A3 is closely associated with the tumor immune microenvironment in human cancers." (PMID 37777564, 2023). "Secondly, high EIF4A3 expression is associated with the immunosuppressive tumor microenvironment and predicts a high anti-PD-L1 therapy response rate." (PMID 37180585, 2023). "The result demonstrated that the SNRPD2 was associated with the tumor-infiltrating immune cells (all P < 0.05), and EIF4A3 was associated with the B cells, CD8+ T cells, neutrophil, and dendritic cells (P < 0.05)." (PMID 35637857, 2022). "Various RBPs induce the upregulation of tumour-associated circRNAs, such as eukaryotic translation initiation factor 4A3 (EIF4A3), which upregulates circMMP9 in GBM." (PMID 35031058, 2022). "Due to the potential role of EIF4A3 in cancer, it is important to further understand its molecular mechanism and association with tumor development." (PMID 34458150, 2021). "The luminal A sub-networks of up-regulated genes pointed to functions associated to genome instability and mutation (EIF4A3), and tumor-promoting inflammation (KPNA2)." (PMID 25625699, 2015). "Additionally, microarray analysis detected high EIF4A3 expression in FAP (+) tumor-associated fibroblasts." (PMID 37777564, 2023). "Furthermore, our analysis also revealed that EIF4A3 expression is notably associated with the tumor microenvironment and immune cell infiltration in different cancer types." (PMID 37777564, 2023). "Moreover, the function of the EIF4A3 was explored in the present study, and the result revealed that the EIF4A3 associated with the several tumor-infiltrating immune cells, including B cells, CD8+ T cells, neutrophil, and dendritic cells." (PMID 35637857, 2022). "We also uncover an unanticipated role of EIF4A3 in the biology of RNA stress granules, which sequester and silence the translation of most mRNAs under stress conditions and are implicated in cell survival and tumour progression." (PMID 31069274, 2019). "Furthermore, our results reveal that upregulation of EIF4A3 expression may be induced under an immunosuppressive state, which is considered a hallmark of tumor progression." (PMID 37180585, 2023). "According to the cancer-promoting effects of hsa_circ_0003763 and EIF4A3, we speculated that overexpression of hsa_circ_0003763 may function as a dynamic scaffolding molecule to enhance the stability of EIF4A3, promoting EIF4A3-associated tumor metastasis." (PMID 34133325, 2021). "CONCLUSIONS: We conclude that OTUB2 deubiquitinates and stabilizes EIF4A3 to promote TNBC progression via TPI1-mediated glycolysis of tumor cells." (PMID 41857621, 2026). "Each unit increase in natural log scale of eIF4a3 resulted in an OR of 1.59 for higher-grade of tumor (99% CI = 1.02–2.50, p-value = 0.008)." (PMID 41563517, 2026). "Other studies have confirmed that some identified RBPs, such as EIF4A3, play a role in cell proliferation, migration, and tumor invasion." (PMID 40809023, 2025). "The results showed that hsa_circ_0058495 effectively rescued the proliferation of tumor cells that had been inhibited by EIF4A3 depletion." (PMID 41041073, 2025).
tumor (continued). "Taken together, EIF4A3 plays an important role in the occurrence and development of tumors and is an important molecule that regulates tumor growth." (PMID 40092703, 2025). "The box plot showed the expression of EIF4A3 in adjacent normal and tumor tissues in TCGA, from which we found that EIF4A3 had higher mRNA expression in tumor samples than in adjacent normal samples." (PMID 40092703, 2025). "Eukaryotic translation initiation factor 4A3 (eIF4A3) regulates mRNA splicing and promotes tumor growth in HCC and other carcinomas." (PMID 39273339, 2024). "In triple‐negative breast cancer (TNBC), circSEPT9 is synthesized with the participation of E2F1 and EIF4A3 proteins and is significantly upregulated in tumor tissues." (PMID 39584047, 2024). "While the majority of studies depicted the oncogenic potentials of EIF4A3, it has also been reported that EIF4A3 regulates circRNAs to exert tumor-suppressive effects." (PMID 39550559, 2024). "At the same time, enhances EIF4A3 and CCL2 expression via positive feedback, induces cSERPINE2 production, and further recruits tumor‐associated macrophages in breast cancer." (PMID 39584047, 2024). "It has been revealed that EIF4A3 exhibits upregulation in a variety of tumours and can facilitate malignant progression, indicating that EIF4A3 can exert a carcinogenic role in cancers." (PMID 39022816, 2024). "EIF4A3 exerts a vital role in tumorigenesis, development, oncogene expression, tumour cell invasion and metastasis." (PMID 39022816, 2024). "Although there is growing evidence indicating the significant involvement of EIF4A3 in both tumor progression and immunity, a thorough analysis of EIF4A3 across different types of cancer has not been carried out." (PMID 38827026, 2024). "EIF4A3 emerges as a promising biomarker with the potential to significantly enhance tumor screening, prognostic evaluation, and the design of individualized treatment strategies across a diverse array of malignancies." (PMID 37777564, 2023). "And immunohistochemistry analysis displayed higher expression level of EIF4A3 in BC tissues compared with adjacent non-tumor tissues." (PMID 37626035, 2023). "We then conducted an in-depth analysis of immune cell infiltration in the tumor microenvironment, revealing a strong correlation between EIF4A3 expression levels and B cell, neutrophil and DC infiltration in most cancer types." (PMID 37777564, 2023). "And western blot results also revealed that EIF4A3 expression was increased in both cancer cell lines and tumor tissues." (PMID 37180585, 2023). "Based on our pan-cancer analysis of EIF4A3, we identified differential expression between tumor and normal tissues, and a significant correlation between EIF4A3 expression and prognosis." (PMID 37777564, 2023). "In gastric cancer, circPITX1 emerges as a driver of tumor proliferation by exerting its regulatory effect on EIF4A3—a factor crucial for tumor growth." (PMID 37841446, 2023). "To further elucidate the relationship between EIF4A3 and the tumor immune microenvironment, we calculated immune infiltration scores and explored immune cell infiltration." (PMID 37777564, 2023). "Thereafter, the association between EIF4A3 expression and the infiltration of immune cells and immune-checkpoint expression was determined using TIMER2 (Tumor Immune Estimation Resource 2) tool." (PMID 37180585, 2023). "To investigate the putative contribution of EIF4A3 to tumor progression and immune response, we probed the expression of EIF4A3 in diverse molecular and immune subtypes in human cancers." (PMID 37777564, 2023). "EIF4A3 was markedly increased in CRC tissues, and its level was positively associated with tumor stage and nodal metastasis based on TCGA data from UALCAN platform." (PMID 37940881, 2023). "We also detected higher expression levels of EIF4A3 in FAP (+) tumor-associated fibroblasts, indicating a potential link between the tumor microenvironment and EIF4A3." (PMID 37777564, 2023).
tumor (continued). "EIF4A3 is consistently elevated in HCC patients and associated with tumour aggressiveness and mortality, through the modulation of FGFR4 splicing." (PMID 36419260, 2022). "Previous studies have also reported strong associations of EIF4A3 with different cell cycle regulatory genes (CDK1 and CDK2), tumor-associated transcription factors, chemokine signaling pathways and spliceosome signaling pathways." (PMID 35139874, 2022). "Collectively, our results reveal that hypoxia-induced circRNF13 mediated by HIF-1α and EIF4A3 promotes tumor progression and glycolysis in PC, indicating the potential of circRNF13 as a prognostic biomarker and therapeutic target for PC." (PMID 36369467, 2022). "Consistently, qPCR confirmed higher rate of dEx2FGFR4/FGFR4 in response to EIF4A3‐silencing in both cell lines treated in vitro, as well as in the Hep3B‐induced in vivo tumours formed in nude mice." (PMID 36419260, 2022). "These functional alterations were associated with changes in the expression of different tumour markers (CCND1, CDKN2A, etc.; determined by qPCR), which were modulated in a cell‐dependent manner in response of EIF4A3‐silencing." (PMID 36419260, 2022). "In particular, EIF4A3‐silencing in vivo in established subcutaneous tumours significantly reduced tumour growth (p‐value < .0001) and final tumour weight compared to scramble‐treated tumours (p‐value < .04)." (PMID 36419260, 2022). "To sum up, we identified EIF4A3-mediated circPRKCI expression acts as a tumor-promoter in TNBC through regulating WBP2 and PI3K/AKT signaling pathway via serving as miR-545-3p sponge, providing a novel providing a new avenue of therapy for TNBC." (PMID 35236829, 2022). "A recent study suggested that overexpression of eIF4A3 was related to poor prognosis, while its dysfunction promoted tumor cell migration, invasion, and drug resistance." (PMID 33924522, 2021). "Further studies on EIF4A3-related tumor molecular mechanisms revealed an important role of EIF4A3 in tumor occurrence, development, and metastasis." (PMID 34458150, 2021). "The results indicated that EIF4A3 functioned as a tumour suppressor and negative regulator of circRNA_100290 in GC." (PMID 34182990, 2021). "Strikingly, eIF4A3-IN-2 treatment dramatically reduced the onsets of bone metastases and decreased bone-metastatic tumor burden compared to vehicle treatment." (PMID 34325714, 2021). "Further research is needed to clarify the role of EIF4A3 in tumor development and identify its potential clinical applications as a diagnostic marker or therapeutic target." (PMID 34458150, 2021). "EIF4A3 inhibition not only reduces tumor proliferation, migration, and angiogenesis, but it also shortens the half-life of VEGFA, suggesting that LINC00667-VEGFA-EIF4A3 is an oncogenic pathway in NSCLC." (PMID 34458150, 2021). "We also found that ALYREF expression was remarkably co-related to eIF4A3 expression, and that eIF4A3 expression was upregulated in HCC tissues compared to adjacent non-tumor tissues." (PMID 34367948, 2021). "Subsequently, the expression of EIF4A3 at cancer stages and tumor grades in the TCGA database showed that EIF4A3 was overexpressed in HCC patients compared with normal people." (PMID 32973867, 2020). "We speculated that LINC01016 may increase the expression of MMP9 through EIF4A3 and played a tumor-promoting role." (PMID 39881131, 2025). "The tumor weight in the EIF4A3-depleted group was significantly lighter than that in the control group, and although the tumors in both groups gradually increased in volume, the tumor volume in the control group were much larger." (PMID 40092703, 2025). "The results showed that EIF4A3 facilitated tumor cell growth." (PMID 41041073, 2025). "The binding of EIF4A3 to the flanking sequence may also prevent back-splicing of certain tumor-suppressive circRNAs." (PMID 39550559, 2024).